CXCL12 (C-X-C motif chemokine ligand 12)
Diseases named in the same sentence as CXCL12 in open-access papers (continued):
Sharing a sentence is not in itself a finding about the gene and the disease.
chronic lymphocytic leukemia (35 papers, 2008 to 2026). "PIK90 has been shown in previous studies to significantly attenuate CXCL12‐induced chemotaxis and actin polymerisation, while also demonstrating efficacy in inducing apoptosis in chronic lymphocytic leukaemia cells." (PMID 40095893, 2025). "The CXCL12/CXCR4/STAT3 pathway can promote the expression of IL-10 in chronic lymphocytic leukemia (CLL) cells, inducing immunosuppression." (PMID 38920657, 2024). "Linking this finding to B cell chemotaxis, IgM stimulation of chronic lymphocytic leukaemia (CLL) B cells decreased CXCL12 chemotaxis." (PMID 36013463, 2022). "Spiegelmer NOX-A12, targeting CXCL12, interferes with the migration and drug resistance of chronic lymphocytic leukemia (CLL), inhibits chemotaxis, and sensitizes CLL cells to cytotoxic drugs." (PMID 36678780, 2022). "The hypoxia-inducible factor 1 (HIF-1) and the CXCL12/CXCR4 axis regulate the interaction of chronic lymphocytic leukemia cells and the tumor microenvironment." (PMID 34207596, 2021). "The NOX-A12 is an antagonist of CXCL12 that binds to the chemokine and disrupts the accumulation of chronic lymphocytic leukemia (CLL) cells in the bone marrow." (PMID 32659966, 2020). "In addition, inhibition of JAK2 or BTK, downstream effectors of CXCL12, inhibits integrin activation and suppresses tumor cell adhesion, survival, and spread in B-cell chronic lymphocytic leukemia (B-CLL)." (PMID 37047140, 2023). "Moreover, CXCL12 signaling has been shown to play a major role in the pathophysiology of chronic lymphocytic leukemia (CLL), especially in the interaction of leukemic cells with the tissue microenvironment." (PMID 25057429, 2013). "Moreover, recent work indicates that Syk is involved in CXCL12- and α4β1 integrin-induced signaling in chronic lymphocytic leukemia." (PMID 21050432, 2010). "CXCL12-expressing CLL-FDCs (e.g Dark-zone FDCs) have been shown to be required for chemotaxis and survival of indolent chronic lymphocytic leukemia, particularly through the production of BAFF." (PMID 40740784, 2025). "T140, and its analogs, inhibit actin polymerization and chemotaxis, suppress CXCL12-induced MAPK activation and STAT3 serine phosphorylation, and impede the migration of chronic lymphocytic leukemia (CLL) cells to stromal cells." (PMID 35893797, 2022). "Homing of chronic lymphocytic leukemia (CLL) cells to sites favoring growth, a critical step in disease progression, is principally coordinated by the CXCL12/CXCR4 axis." (PMID 36139103, 2022). "CXCL12 is an essential retention and homing signal for highly CXCR4-expressing chronic lymphocytic leukemia (CLL) cells in tissues such as the bone marrow." (PMID 34503058, 2021). "In chronic lymphocytic leukemia (CLL), the CXCL12/CXCR4 axis induces immune suppression via Signal Transducer and Activator of Transcription 3 (STAT3) phosphorylation in B and T-CLL cells." (PMID 32260318, 2020). "The interaction of cancer cells with the surrounding microenvironment plays a critical role in chronic lymphocytic leukemia (CLL), and MM cells utilize the CXCR4/CXCL12 axis for bone marrow homing." (PMID 35056696, 2022).
COVID-19 (34 papers, 2020 to 2025). A disease caused by infection with severe acute respiratory syndrome coronavirus 2. "The combined variants (CT + TT) of CXCL12 were found to be independent predictors to severe or critical COVID-19 risk with P value = < 0.001, OR = 3.034& 95% CI = 1.805–5.098." (PMID 37858116, 2023). "Multivariate logistic regression analysis showed that the combined variants (CT + TT) of CXCL12 were found to be independent predictors to severe or critical COVID-19 risk with P value = < 0.001, OR = 3.034& 95% CI = 1.805–5.098." (PMID 37858116, 2023). "This study aims to assess the potential association between the CXCL12 rs2839693 polymorphism and the severity of COVID-19 in Assiut University Quarantine Hospital during the period from May 2022 to August 2022." (PMID 37858116, 2023). "This study aimed to assess the potential association between the CXCL12 rs2839693 polymorphism and the severity of COVID-19 in Assiut University Quarantine Hospital in the period from May 2022 to August 2022." (PMID 37858116, 2023). "CXCL12 polymorphisms could potentially impact the ability to clear the virus from the body, affecting the duration and severity of COVID-19." (PMID 37858116, 2023). "Gene polymorphisms in CXCL12 might lead to differences in immune cell recruitment and activation, which could affect the immune response to the virus and the development of severe COVID-19." (PMID 37858116, 2023). "Together, these data are consistent with the notion that CXCL12 regulates CD16int LDN accumulation in the circulation of COVID-19 survivors who have elevated numbers of CD16int LDNs." (PMID 39773555, 2025). "In our study, some markers of the intussusceptive vascular remodeling typical for COVID-19 were upregulated during the acute (Ccl12, Gdf15, and Cd163) or chronic phase (Col3a1, Cxcl12)." (PMID 40021627, 2025). "As LDNs account for a substantial portion of neutrophils in the lung parenchyma, these findings support the conclusion that CXCL12 plays a regulatory role in COVID-19 immunopathogenesis." (PMID 39773555, 2025). "Our findings revealed that CXCL12 rs2839693 had a role in the development and seriousness of COVID-19." (PMID 37858116, 2023). "Previous studies have found higher levels of CXCL12 in the blood of severe COVID-19 patients hospitalized in critical care units when compared to hospitalized patients with mild to moderate illness and/or healthy controls." (PMID 37858116, 2023). "The present study recommends studying other SNPs in the CXCL12 gene and their relationship with COVID-19 pathogenicity and severity." (PMID 37858116, 2023). "A decreased abundance of a cluster of several leukocyte chemotactic factors (MCP-4, CXCL12, CCL11, CCL19, CCL25, and CCL20) was observed in the COVID-19 cases and associated with a decrease in the cytotoxic T-cell marker CD8A." (PMID 34710339, 2022). "However, excessive CXCL13 levels are probably associated with an inadequate immune response that might be associated with severe COVID-19, while the reduced CXCL12 levels in hospitalized patients might be associated with an increased consumption by GC B cells, indicating a massive B cell response." (PMID 36560669, 2022). "In our cohort, 3 severe COVID-19 patients, with higher levels of CXCL12, had sepsis or bacterial superinfection." (PMID 35087533, 2021). "miR-146a-5p, miR-221-3p and their target CXCL12 (according to miRTarBase), were downregulated in COVID-19 patients." (PMID 35087533, 2021). "C-C motif chemokine 14, C-C motif chemokine 18, and C-X-C motif chemokine ligand 12 were dramatically down-regulated in COVID-19 patients, indicating decreased monocyte activation, B cell migration, and T cell-mediated immune response." (PMID 33203833, 2020). "Additionally, increased plasma CXCL12 levels correlated with decreased numbers of circulating LDNs in a subset of COVID-19 patients who ultimately survived their disease." (PMID 39773555, 2025).
COVID-19 (continued). "Notably, the negative correlation in the blood and lungs between LDN numbers and CXCL12 expression was also observed in COVID-19 survivors." (PMID 39773555, 2025). "In additional experiments, we also investigated the potential action of the nutraceutical formula on other inflammatory genes with a role in innate immunity (i.e., C3, IL-1β, IL-6, CXCL10 and CXCL12) whose modulation have been reported in COVID-19 pathogenesis and progression." (PMID 38886736, 2024). "Our data indicated the signature of CXCL12 rs2839693 in the pathogenesis and severity of COVID-19." (PMID 37858116, 2023). "The frequency of the TT genotype and the T allele was higher in the severe or critical group than in the mild or moderate which may indicate the role of CXCL12 rs2839693 in the pathogenesis and severity of COVID-19." (PMID 37858116, 2023). "Prolonged CXCL12 activity may not only improve leukocyte chemotaxis, which is advantageous, but it may also worsen the chronic inflammation identified in COVID-19." (PMID 37858116, 2023). "Moreover, blood neutrophils from COVID-19 patients were hyper-responsive to CXCL12 in shape change assays in comparison to neutrophils from healthy controls." (PMID 36725964, 2023). "Finally, in COVID-19, CXCL12 plasma levels were shown to be significantly elevated in patients in ICU compared to healthy volunteers and patients with mild COVID-19." (PMID 36725964, 2023). "The expression of CXCL12 is elevated in the Fibroblasts from severe COVID-19 patients which may help to attract immune cells with the CXCR4 receptor, such as macrophages, T cells, and NK cells." (PMID 37858116, 2023). "Intriguingly, we observed increased levels of the chemokine CXCL12 in CAP vs. COVID-19 patients." (PMID 35087533, 2021). "The chemokine CXCL12 was also increased in severe vs. mild COVID-19." (PMID 35087533, 2021). "Thus, we cannot rule out the relationship between higher levels of this chemokine and the presence of superinfection or sepsis in critically ill COVID-19 patients, since CXCL12 has a role in neutrophil recruitment from bone marrow." (PMID 35087533, 2021). "Moreover, CXCL12 was found at higher levels in the plasma of severe vs. mild COVID-19 patients." (PMID 35087533, 2021). "Six chemokines (CXCL9, CXCL10, CCL4, CCL5, CCL27, and CXCL12) and eight interleukins (IL-1Ra, IL-2Ra, IL-3, IL-5, IL-9, IL-12p40, IL-15, and IL-16) were increased in both PLWH/COVID-19 and COVID-19-only." (PMID 41516165, 2025). "In BAL fluids, elevated levels of CXCL12 in ICU patients with severe COVID-19 compared to ICU patients with influenza were observed, together with upregulation of CXCR4 on COVID-19 BAL fluid neutrophils." (PMID 36725964, 2023). "Therefore, we proposed that CXCL12 could influence the results and severity of COVID-19." (PMID 37858116, 2023). "Search for targets of these miRNAs, combined with plasma protein measurements, identified a differential cytokine signature between COVID-19 and CAP that included EGFR, CXCL12 and IL-10." (PMID 35087533, 2021). "Significant differences were also detected in plasma levels of CXCL12, IL-17, TIMP-2 and IL-21R between mild and severe COVID-19 patients." (PMID 35087533, 2021). "Similarly, dysregulated TNF-α release results in apoptosis-promoting effects on highly activated effector T cells, and also increases the adhesion of lymphocytes in ALI by activating the SDF-1(CXCL12)/CXCR4 pathway, possibly also explaining decreased T cell counts (lymphopenia) in severe COVID-19." (PMID 33604758, 2021). "Mechanistically, IL-3 increases innate antiviral immunity by promoting the recruitment of circulating pDCs into the airways by stimulating CXCL12 secretion from pulmonary CD123+ epithelial cells, both, in mice and in COVID-19 negative patients exhibiting pulmonary diseases." (PMID 33602937, 2021).
ischemic stroke (33 papers, 2012 to 2026). A stroke disorder caused by obstruction of blood flow to the brain, due to thrombotic (local blood clot formation) or embolic (due to a blood clot or other material traveling from another site) event. "To address these challenges, we engineered ASCs with CXCL12 variants and aimed to generate a synergistic effect in improving ischemic stroke outcomes." (PMID 38255866, 2024). "Our study highlights the remarkable potential of mouse-derived ASC transplantation, engineered with the monomeric CXCL12 variant, in enhancing neurobehavioral recovery following ischemic stroke." (PMID 38255866, 2024). "There were no significant genetic associations observed among rs17465637 (MIA3) or rs501120 (CXCL12) and future adverse CV events, including MI, ischemic stroke, CV death and major adverse cardiovascular events (MACEs)." (PMID 31804579, 2019). "Thus, we adopted virus-carrying variant genes of CXCL12 to transfect ASCs and analyzed a wider treatment time window for ischemic stroke." (PMID 38255866, 2024). "However, the cumulative effects of ASCs when combined with various structures of CXCL12 on ischemic stroke and its underlying molecular mechanisms remain unclear." (PMID 38255866, 2024). "Twelve genes have been reported as potential regulators of HT in ischemic stroke in previous studies: Casp3, Csf2, Ctnnb1, Cxcl12, Hif1a, Il1b, Mtor, Ptgs2, Ptprc, Tlr2, Tlr4, and Vcam1." (PMID 40002863, 2025). "This study introduces an innovative approach to enhance the therapeutic potential of ASCs in treating ischemic stroke by genetically engineering them with the monomeric structure of CXCL12." (PMID 38255866, 2024). "The expression of CXCR7 and its ligand CXCL12 are increased post-ischemic stroke, as CXCL12 and CXCR7 have neuroprotective effects." (PMID 32098047, 2020). "The CXCL12/CXCR4 axis plays an important role in the treatment of ischemic stroke with transplanting BMSCs." (PMID 33381162, 2020). "Studies have shown that CXCL12 stimulates pro-inflammatory response in the acute phase of ischemic stroke by binding to the CXCR4 receptor." (PMID 31514749, 2019). "The IL-17 and CXCL12 produced by γδ T cells further drive neutrophil infiltration and monocyte/macrophage migration to the lesion site, respectively, exacerbating secondary injury and contributing to ischemic stroke progression." (PMID 40746532, 2025). "The chemokine CXCL12/SDF1 has been found to play important roles in several processes involved in ischemic stroke and its’ subsequent repair, brain tumor pathogenesis, human immunodeficiency virus (HIV) encephalopathy, Multiple Sclerosis and stem cell migration." (PMID 24808825, 2014). "In a rat model of ischemic stroke, hypoxic preconditioning of bone marrow MSCs (BMSCs) improved their ability to promote cell homing, neuronal differentiation and regeneration, and the recovery of neuronal function via CXCL12/CXC chemokine receptor type 4 (CXCR4) signaling." (PMID 34490053, 2021). "Our study has demonstrated that the transplantation of ASCs engineered with CXCL12 monomers results in the upregulation of VEGF and bFGF expression in the mouse brain following an ischemic stroke." (PMID 38255866, 2024). "BBB-derived CXCL12/CXCR4 signaling promoted NK cell migration and improved functional outcomes after ischemic stroke in mice." (PMID 37817190, 2023). "Stromal-derived factor-1 (SDF-1, also known as CXCL12) and its receptors CXCR4 and CXCR7 play important roles in brain repair after ischemic stroke, as SDF-1/ CXCR4/CXCR7 chemokine signaling is critical for recruiting stem cells to sites of ischemic injury." (PMID 29896417, 2018). "CXCL12 is constitutively expressed at the blood–brain barrier (BBB) by endothelial cells and redistributed in location during EAE in mice or multiple sclerosis in humans, however a role for BBB-derived CXCL12 during ischemic stroke was not known." (PMID 36631780, 2023).
ischemic stroke (continued). "Furthermore, some other studies have reported that CXCL-12/CXCR4 reduced neuronal apoptosis after traumatic brain injury and ischemic stroke." (PMID 34795842, 2021).
coronary artery disease (32 papers, 2011 to 2026). "GREX of ABCA1 and CXCL12 was significantly associated with atherosclerotic phenotypes, including ischemic heart disease and coronary atherosclerosis in individuals of European genetic ancestry (n=65, 364, p<0.0044)." (PMID 39483879, 2024). "However, some studies have suggested that CXCL12 gene may affect the risk of coronary heart disease." (PMID 28903360, 2017). "Clinical studies have also demonstrated a close relationship between CXCL12 and the severity of coronary artery disease." (PMID 38475787, 2024). "From a clinical translational perspective, human genome-wide association studies (GWAS) in over 100,000 people have identified two novel loci downstream of the CXCL12 gene locus associated with coronary artery disease (CAD) and MI, implicating an essential role in cardiovascular disease (CVD)." (PMID 34072818, 2021). "Intramyocardial delivery of CXCL12 in phase 1 and phase 2 clinical trials in ischemic heart disease showed clinical improvement, suggesting therapeutic benefits of CXCL12." (PMID 34072818, 2021). "CCL3, CCL18, CXCL12/SDF-1, CXCL16, IGF1 and IL10 have been linked to pro-angiogenesis and/or coronary artery diseases." (PMID 23496821, 2013). "We hypothesize that these compounds can modify CXCL12/CXCR4/CXCR7 pathway offering benefits for coronary artery disease patients." (PMID 35120520, 2022). "Recently, administration of Cxcl12 to injured hearts, a chemokine that binds the receptor Cxcr4 and is key for EC chemotactic migration, has shown a significant effect on the development of collateral arteries in ischemic heart disease." (PMID 33078209, 2021). "In patients with coronary artery disease, statins have been associated with down-regulation of several chemokine ligands, but their potential effect on CXCL12, a potent mediator of angiogenesis, has not been reported previously." (PMID 23369699, 2012). "Tan IIA has been shown to increase CXCL12 expression at the site of injury as well as CXCR4 on transplanted MSCs, leading to enhanced MSC migration to the injured area, which may prove effective in the treatment of ischemic heart disease." (PMID 32582713, 2020).